HDAC6 (histone deacetylase 6)
Diseases named in the same sentence as HDAC6 in open-access papers (continued):
Sharing a sentence is not in itself a finding about the gene and the disease.
cancer (continued). "It would be of interest to optimize compound MPT0B451 for its inhibition selectivity in HDAC6 and validate the anti-cancer effect in cancer cell lines or patient derived cells resistant to MTAs." (PMID 29593536, 2018). "Inhibition of HDAC6 confers a cancer immunotherapeutic response by regulating immune checkpoint markers within the tumor microenvironment." (PMID 30096875, 2018). "Inhibitors of HDAC6 display anti-tumor activity in various cancer models; thus, HDAC6 inhibition is being considered as an add-on treatment to inhibit tumor growth." (PMID 30270813, 2018). "HDAC6 has also been studied in cancer especially for its ability to coordinate a variety of cellular processes that are important for cancer pathogenesis." (PMID 30096875, 2018). "HDAC inhibitors in general, and HDAC6 inhibitors specifically, have been looked at as promising tools for the development of anti-cancer drugs in their own right." (PMID 29690504, 2018). "HDAC6 can participate in the process of tumorigenesis and development through various pathways, such as oncogenic cell transformation and cancer cell migration and invasion." (PMID 30176876, 2018). "Here, we review the unique features of HDAC6 and its role in cancer, which make HDAC6 an appealing drug target." (PMID 30176876, 2018). "Compound 23BB as a highly selective HDAC6 inhibitor was designed, synthesized by our lab and exhibited therapeutic potential in various cancer models with good safety." (PMID 29632491, 2018). "We integrated the epigenetic characters of HDAC6 and a cancer-related signaling pathway to explore the potential mechanisms of these occurrences." (PMID 30050135, 2018). "These immunoblot results are in agreement with human protein atlas data, suggesting differential expression pattern of HDAC6 & HDAC8 in different cancer cell lines, assigning their specific/independent roles in deacetylating their target substrates." (PMID 29716651, 2018). "Ricolinostat (ACY-1215), a first-in-class selective HDAC6 inhibitor, exhibits antitumor effects alone or in combination with other drugs in various cancers." (PMID 30050135, 2018). "HDAC6 has also been studied in cancers especially for its ability to coordinate a variety of cellular processes that are important for cancer pathogenesis." (PMID 30096875, 2018). "Many types of cancers express high levels of HDAC6, and this overexpression can be exploited for treatment purposes." (PMID 30594243, 2018). "Considering the implication of HDAC6 in cancer progression, this isoenzyme represents a good pharmacological target for selective inhibition potentially reducing the toxicity related to the off-target effects of pan-HDAC inhibitors." (PMID 30096875, 2018). "Several selective HDAC6 inhibitors are currently in clinical trials for cancer treatment and bring hope for patients with malignant tumors." (PMID 30176876, 2018). "In addition, the HDAC6 activity can affect the gene expression of some critical immune system molecules, including tumor-associated antigens, programmed death receptor-1 (PD-1), and programmed death receptor ligand-1 (PD-L1), which are central targets in cancer immunotherapy." (PMID 30176876, 2018). "HDAC6 overexpression correlates with tumorigenesis, and improves the survival of cancer cells, which presupposes a cell protective function." (PMID 29511309, 2018). "Tubacin inhibits HDAC6-targeted α-tubulin deacetylation and migration in cancer cells expressing HDAC6." (PMID 30332838, 2018). "In this study, we showed that MPT0B451, a novel 1-benzylindole derivative inhibitor, selectively inhibits HDAC6 activity and microtubule assembly to facilitate the efficacy in anti-cancer treatment." (PMID 29593536, 2018). "This study shows that the hydroxamate-based small-molecule C1A can phenocopy HDAC6 inhibition and modulate autophagy in cancer cells from different origins." (PMID 30318510, 2018).
cancer (continued). "This unique activity profile of tubacin is predicted to contribute to its anti-proliferative and pro-apoptotic effects and make it a superior anti-cancer agent compared to compounds such as tubastatin A that are more HDAC6-specific." (PMID 29423038, 2018). "With respect to HDAC6, it is also able to inhibit cancer cell migration by removing RelA acetylation." (PMID 29038521, 2017). "HDAC6 inhibition has recently emerged as an attractive target for the treatment of cancer and other chronic diseases." (PMID 29179471, 2017). "HDAC6, a class IIb HDAC, is a key regulator of many signaling pathways that are associated to cancer, thereby making HDAC6 an attractive target." (PMID 28315173, 2017). "We found that the proteasome inhibitor MG132, or the Cullin-based E3 ligases inhibitor MLN4924, but not the autophagosome-lysosome inhibitor bafilomycin A1, stabilized endogenous HDAC6 protein in multiple cancer cell lines." (PMID 28599312, 2017). "Aberrant expression patterns of HDAC6 are found in various cancers, including breast cancer, oral squamous cell carcinoma, ovarian cancer, GBM, and mouse tumor models." (PMID 28099914, 2017). "As reviewed by Aldana-Masangkay and Sakamoto, HDAC6 expression was upregulated in diverse tumors and cancer cell lines." (PMID 28052127, 2017). "Given its characterized oncogenic role, HDAC6 has become a promising drug target to treat human cancers, and several HDAC6 specific inhibitors have entered into clinical trials, such as ACY-1215 and ACY-241." (PMID 28599312, 2017). "HDAC6 is known to promote many aspects of cancer development such as cell transformation and angiogenesis, and therefore HDAC6 has become a major target for therapeutic interventions to treat cancer." (PMID 28659384, 2017). "Since then, HDAC6 has become a target for cancer therapy due to its pivotal role in oncogenic cellular transformation." (PMID 28915616, 2017). "HDAC6 expression is also required to maintain anchorage-independent growth of established cancer cell lines." (PMID 28668087, 2017). "Functionally, we demonstrated that the tumor suppressor SPOP suppresses the cancer cell proliferation and migration partly through negatively regulating the stability of HDAC6." (PMID 28599312, 2017). "HDAC6 is a cytoplasmic histone deacetylase regulating multiple pro-survival mechanisms and overexpressed in response to stress in cancer cells." (PMID 28674407, 2017). "HDAC6 is involved in cell motility and catalyzes α-tubulin deacetylation, and thus, the enzyme also promotes cancer cell metastasis." (PMID 26747087, 2016). "It has been reported that in cancer cells the targeting of histone deacetylase 6 (HDAC6) expression or its activity reduces CD133 stability and signalling, resulting in reduced tumorigenesis." (PMID 27247576, 2016). "Over the past decade, HDAC6 has emerged as an attractive target for the treatment of a variety of diseases, including neurodegenerative disorders and cancer." (PMID 27028867, 2016). "Among different HDAC isoforms, HDAC6 has been shown to play a role in the de-acetylation and cytoplasmic retention of survivin in cancer cells." (PMID 27065869, 2016). "HDAC6 inhibition has been proposed as the molecular basis for synergism of HDACi with other anti-cancer agents that act through proteasome/aggresome deregulation." (PMID 27423454, 2016). "In detail, SP acts on the ROCK/HDAC6 pathway involved in dedifferentiation and invasiveness of undifferentiated human cancers, by restoring its physiological activity level." (PMID 26415230, 2015). "The central involvement of HDAC6 in aggresome formation and clearance makes HDAC6 one of the most interesting druggable targets for the induction of proteotoxicity in cancer cells." (PMID 25759792, 2015).
cancer (continued). "For cancer cells it was demonstrated that increased tubulin acetylation by HDAC6 inhibition suppressed proliferation." (PMID 26448568, 2015). "Previous studies have shown that histone deacetylase 6 (HDAC6) plays critical roles in many cellular processes related to cancer." (PMID 25774669, 2015). "HDAC6 plays an important role in many cellular processes related to cancer, including the cell stress response, cell migration and motility and cancer-related signaling pathways." (PMID 25774669, 2015). "Although the potency of these compounds was lower compared to known HDACi TSA, apicidin and depsipeptide, they had comparable or greater selectivity of inhibition for cancer vs. normal cells and for HDAC6 vs HDAC1." (PMID 26698121, 2015). "Transwell migration assays further revealed that HDAC6 siRNAs dramatically reduced the amount of cancer cells to migrate across the porous membrane." (PMID 24474193, 2014). "Over the past decade, there has been tremendous effort to develop effective and specific HDAC6 inhibitors for the treatment of human diseases including cancer, although their mechanisms of action remain largely elusive." (PMID 24474193, 2014). "CD133 forms a stable protein complex with HDAC6 and β-catenin, which leads to the activation of β-catenin signaling targets in different types of cancer." (PMID 24427168, 2014). "In cancer cells, the deacetylase HDAC6 directly interacts with and regulates the intracellular localization of CD133." (PMID 24427168, 2014). "We also investigated the effects of HDAC6 siRNAs on the cell cycle progression of cancer cells by flow cytometric analysis of DNA content." (PMID 24474193, 2014). "The special class IIb histone deacetylase, HDAC6, plays a prominent role in many cellular processes related to cancer, including oncogenesis, the cell stress response, motility, and myriad signaling pathways." (PMID 23644884, 2013). "We therefore tested several human cancer cell lines and found that Hdac6 exhibited significant nuclear localization in each of the cell lines." (PMID 24302573, 2013). "Unlike differentiated cells, where Hdac6 is mainly cytoplasmic, Hdac6 is largely nuclear in ESCs, neural stem cells (NSCs), and some cancer cell lines, and interacts with Tip60-p400 in each." (PMID 24302573, 2013). "A few thiolate analogues with bulky alkyl and tert-butylcarbamate groups showed effective HDAC6 and cancer cell growth inhibition." (PMID 23644884, 2013). "Researchers still continue their work in the effort to manipulate cell death and the cell cycle, and hence cancer, through inhibition of HDAC6." (PMID 23644884, 2013). "Together, these data suggest that Hdac6 functions within Tip60-p400 complex in some types of cancer, and support the idea that stem cells and some cancer cells share several common phenotypes and regulatory pathways." (PMID 24302573, 2013). "The search for potent HDAC6 inhibitors to block cancer cell proliferation continued strong through 2007." (PMID 23644884, 2013). "In this study, we showed that Hdac6 interacts with Tip60-p400 complex in ESCs, NSCs, and some cancer cell types, and is necessary for the proper regulation of most genes regulated by Tip60-p400 in ESCs." (PMID 24302573, 2013). "Despite growing evidence indicating a role for HDAC6 in cancer invasion, inducers of HDAC6 activity are still poorly characterized." (PMID 23405166, 2013). "While Hdac6 localizes to the cytoplasm of normal somatic cells, nuclear Hdac6 has been observed in some cancers, in particular within tumors that are poorly differentiated." (PMID 24302573, 2013). "Overexpression of HDAC6 is frequently correlated with the tumor development, and hence HDAC6 is considered to be a target for cancer therapy." (PMID 24156782, 2013). "HDAC6, a unique cytoplasmic member of class II, has become a target for drug development to treat cancer due to its major contribution in oncogenic cell transformation." (PMID 22384180, 2012).
cancer (continued). "Moreover, HDAC6-selective drug candidates appear to be reasonably well tolerated in human cancer patients." (PMID 41330635, 2026). "In addition to its critical role in regulating microtubule dynamics and promoting cancer cell migration and invasion, HDAC6 influences other key oncogenic processes, including DNA damage response, apoptosis, and interactions with tumour suppressor pathways." (PMID 39941046, 2025). "Consequently, the rational design of novel, HDAC6-based multi-target agents is under development as a way to maximise the effects of HDAC6 inhibition for treating cancer." (PMID 39941046, 2025). "The specific application of HDAC6 inhibition in cancer remains uncertain, and there is considerable debate regarding the selectivity of HDAC6-targeting compounds, such as ricolinostat, which exhibit antiproliferative effects at concentrations exceeding the drug’s selective range." (PMID 39941046, 2025). "Combinations of HDACi, such as ACY-241 (a moderately selective HDAC6 inhibitor) or Entinostat (a class I inhibitor) with anti PD-1/PD-L1 antibodies have been tested in several clinical trials to treat various cancers (e.g. clinical trial reference: NCT02635061, NCT02915523, NCT02697630)." (PMID 40433358, 2025). "HDAC6 is a potential therapeutic target in diseases such as cancer and neurodegenerative disorders." (PMID 40542929, 2025). "Further evaluations can be made as to whether HDAC6-dependency is subtype or stages-specific, or generalizable to other radioresistant cancers." (PMID 39800760, 2025). "Considering the constitutive activation of EGFR signalling in cancer drives cell proliferation, resistance to chemotherapy, and metastasis, HDAC6 responses may also contribute to EGFR responses in cancer." (PMID 39941046, 2025). "In addition, cancer cells often survive HDAC6 gene knockout, in contrast to the cytotoxic responses induced by catalytic domain inhibitors." (PMID 39941046, 2025). "In recent years, the selective inhibition of HDAC6 has garnered considerable interest as a therapeutic strategy to attenuate tumor progression, suppress metastasis, and overcome drug resistance—particularly in preclinical models of cancer." (PMID 41011174, 2025). "While pan‐HDAC degraders could be developed to treat multiple cancers, selective HDAC6 PROTACs, like selective HDAC6 inhibitors, could be used in neurodegenerative diseases, inflammatory diseases, and some cancers." (PMID 39973224, 2025). "Thus, in response to dietary valine restriction, HDAC6 induces both DNA demethylation and DNA damage, highlighting its potential as a target of cancer therapy." (PMID 40843669, 2025). "Additionally, phenotypic responses to HDAC6 inhibition differ from those following HDAC6 gene knockdown, further complicating our understanding of its role in cancer." (PMID 39941046, 2025). "Both the catalytic and noncatalytic functions of HDAC6 have been implicated in cancer development and progression." (PMID 39941046, 2025). "These bifunctional molecules could induce the degradation of HDAC6, demonstrating potential for the treatment of various cancers and inflammatory disorders." (PMID 40013582, 2025). "HDAC6 has recently emerged as a major target in cancer immunotherapy because of its role in regulating the transcriptional activity of STAT3 and expression of a range of immune signalling proteins, most notably, cell death protein-1 (PD-1) and programmed death ligand 1 (PD-L1)." (PMID 39941046, 2025). "As a result, effective inhibition of HDAC6 in cancer using small molecule inhibitors requires a more sophisticated understanding of its role within tumour cells, including whether its expression correlates with deacetylase activity." (PMID 39941046, 2025). "Immunofluorescent assay presented that the gRNAs of HDAC6 combined with dCas13b‐ALKBH5 could significantly increase the cilia length of cancer cells." (PMID 39535388, 2025).
cancer (continued). "These diverse functions make HDAC6 essential for maintaining cellular homeostasis and responding to stress while also establishing it as a compelling therapeutic target in diseases such as cancer, neurodegeneration, and inflammation." (PMID 41011174, 2025). "Furthermore, HDAC6 inhibition enhanced the sensitivity of cancer cells to anti-PD-L1 blockade by reducing the number of M2 macrophages, which negatively regulate the immune response." (PMID 39063958, 2024). "In this regard, small molecule inhibitors of AurA and HDAC6 have been tested in clinical trials for treatment of cancer and neurodegenerative disease and could serve as the basis for a novel class of anti-chlamydial antibiotics." (PMID 38885287, 2024). "It will be interesting to examine the role of HDAC6 in anti-cancer drug resistance in the future." (PMID 38920983, 2024). "In particular, HDAC6 regulates a number of substrates, including heat shock protein 90 (Hsp90), which is a chaperone protein involved in the correct folding of many proteins, some of them being cancer-relevant targets." (PMID 39204176, 2024). "Additionally, HDAC6 prevents apoptosis in cancer cells by regulating Chk1, a cell cycle checkpoint protein, and Ku70, a non-histone protein involved in DNA damage repair." (PMID 39063958, 2024). "Besides the role of acetylation in regulating normal cellular activity, there has been a plethora of studies indicating the involvement of HDAC6 in tumorigenesis and the development of cancer cells." (PMID 38918466, 2024). "Additionally, within the HDAC family, HDAC1 predominantly assumes a pro-cancer function, whereas HDAC6 potentially serves as an anticancer factor." (PMID 38490978, 2024). "However, given the role that HDAC6 exerts in this process in other cancers, it is conceivable that GBM spreading and invasion of the surrounding brain tissue would, at least in part, depend on HDAC6 activity." (PMID 39595195, 2024). "Among them, HDAC6, a histone deacetylase, has become an important therapeutic target for cancer." (PMID 39411320, 2024). "The role of HDAC6 in cancer has been extensively reviewed elsewhere." (PMID 39595195, 2024). "The dual inhibition of ROCK and HDAC6 can, therefore, achieve two effects: stabilization of the microtubule network by enhancing tubulin acetylation and prevention of cancer cell migration by disrupting actin cytoskeleton dynamics and stabilizing microtubule dynamics." (PMID 39458584, 2024). "Finally, in tumour microenvironments, the down-regulation of miR-548m has been linked with the activation of c-Myc, which subsequently up-regulated HDAC6, resulting in stroma-mediated survival of cancer cell." (PMID 38203740, 2024). "Moreover, HDAC6 is a multisubstrate enzyme that controls several cellular processes, including those that lead to cancer, neurological illnesses and inflammatory disorders." (PMID 37638049, 2023). "HDAC6 inhibition elevates the level of Bax, which activates caspase‐3/caspase‐9 and enables the release of cytochrome C from mitochondria to the cytoplasm, leading to apoptosis in cancer cells." (PMID 36749475, 2023). "The acetylation of Prx increases its reductase activity, thus, HDAC6 and Prx may be considered as therapeutic targets for modulating intracellular redox status in cancer." (PMID 38258065, 2023). "Beyond the role of C15:0 as an mTOR inhibitor and AMPK activator, C15:0 supports healthy cellular signaling as a dual partial PPAR α/δ agonist, JAK-STAT inhibitor, and HDAC6 inhibitor, which are well-established moderators of metabolism, lipids, inflammation, and cancer." (PMID 37960259, 2023). "Interestingly, HDAC6 inhibitors also show immunomodulatory properties with potential to be used as therapeutic agents for cancer immunotherapy." (PMID 37446224, 2023). "As a result, HDAC6 inhibition contributed to attenuating in vitro 2D and 3D cancer cell growth." (PMID 36639650, 2023).